RNU6-92P (RNA, U6 small nuclear 92, pseudogene)
Gene: Small nuclear RNA gene on chromosome 7 (133,082,829 to 133,082,932, forward strand). Ensembl gene ENSG00000272393.
Homologues: Orthologues: chimpanzee U6 (99% identical), macaque U6 (89% identical), rat LOC120097203 (62% identical), mouse Gm54806 (62% identical). Paralogues in human: RNU6-115P (81% identical), RNU6-1209P (81% identical), RNU6-66P (80% identical), RNU6-797P (80% identical), RNU6-1022P (79% identical), RNU6-1025P (79% identical), RNU6-1046P (79% identical), RNU6-1094P (79% identical), RNU6-1159P (79% identical), RNU6-500P (79% identical), RNU6-59P (79% identical), RNU6-776P (79% identical), and 1287 more.